FUCA1 (alpha-L-fucosidase 1)
Description:
Alpha-L-fucosidase is responsible for hydrolyzing the alpha-1,6-linked fucose joined to the reducing-end N-acetylglucosamine of the carbohydrate moieties of glycoproteins.
Synonyms: FUCA
Tractability: Small molecule: a structure with a bound ligand is known; a high-quality ligand is known; it belongs to a druggable protein family. Antibody: its Gene Ontology location is reachable by antibodies, with high confidence; UniProt predicts a signal peptide or a membrane-spanning region. PROTAC: its protein half-life has been measured; a small molecule that binds it is known.
Target class: Enzyme; Hydrolase
Gene: Protein-coding gene on chromosome 1 (23,845,077 to 23,868,356, reverse strand). Ensembl gene ENSG00000179163.
Subcellular location: Lysosome
Subcellular location (Human Protein Atlas): Vesicles
Pathways (Reactome):
Immune System: Neutrophil degranulation
Metabolism of proteins: Reactions specific to the complex N-glycan synthesis pathway
Gene Ontology:
Molecular function: alpha-L-fucosidase activity; protein binding
Biological process: fucose metabolic process; glycoside catabolic process; glycolipid catabolic process; carbohydrate metabolic process
Cellular component: extracellular exosome; lysosome; azurophil granule lumen; cytoplasm; extracellular region; lysosomal lumen
Genetic constraint (gnomAD): Loss-of-function variants: 47 observed, 51.57 expected, observed/expected ratio (o/e) 0.91, 90% interval 0.72 to 1.16. The upper end of that interval is the gene's LOEUF score, 1.16, which puts it in group 5 of 6, group 1 being the genes least tolerant of losing a copy. Missense variants: 544 observed, 580.84 expected, observed/expected ratio (o/e) 0.94, 90% interval 0.87 to 1. Synonymous variants: 223 observed, 214.42 expected, observed/expected ratio (o/e) 1.04, 90% interval 0.93 to 1.16.
Gene-disease validity (ClinGen):
ClinGen rates the evidence that FUCA1 causes each of these diseases.
fucosidosis (autosomal recessive): Definitive.
Homologues: Orthologues: chimpanzee FUCA1 (99% identical), macaque FUCA1 (97% identical), dog FUCA1 (83% identical), guinea pig FUCA1 (82% identical), pig FUCA1 (82% identical), mouse Fuca1 (81% identical), rabbit FUCA1 (80% identical), rat Fuca1 (78% identical), tropical clawed frog fuca1 (68% identical), zebrafish fuca1.1 (62% identical), zebrafish fuca1.2 (62% identical), Drosophila melanogaster Fuca (47% identical), and 1 more. Paralogues in human: FUCA2 (54% identical).
Diseases named in the same sentence as FUCA1 in open-access papers:
FUCA1 is named in the same sentence as 58 diseases in open-access papers, as found by Europe PMC text mining. Sharing a sentence is not in itself a finding about the gene and the disease. The quoted sentences say what the papers report.
fucosidosis (21 papers, 2015 to 2026). "Fucosidosis is caused by homozygous or, in rare cases, compound heterozygous mutations in the FUCA1 gene, which lead to a severely reduced function or loss of function of the FUCA1 protein." (PMID 41200823, 2026). "This study lays the groundwork for individualized TR therapy for patients with fucosidosis with FUCA1 nonsense variants." (PMID 41200823, 2026). "In this study, we examined the use of TR induction at pathogenic PTCs in the FUCA1 gene as a basis for the development of an individualized fucosidosis therapy." (PMID 41200823, 2026). "It was later thought that this clinical variability was not only due to different allelic mutations in FUCA1, but additional factors also contributed to the phenotype of the fucosidosis patient." (PMID 39796208, 2025). "We report a 4‐year‐old boy with fucosidosis with novel pathogenic FUCA1 variants and neuroanatomical correlates." (PMID 39865383, 2025). "We describe a new case with fucosidosis, associated with two novel pathogenic variants of the FUCA1 gene." (PMID 39865383, 2025). "Fucosidosis is a rare lysosomal storage disease caused by α-L-fucosidase deficiency following a mutation in the FUCA1 gene." (PMID 39796208, 2025). "In this report, we present a 4‐year‐old Spanish boy with fucosidosis, novel pathogenic FUCA1 variants, and unique neuroimaging findings." (PMID 39865383, 2025). "Fucosidosis (OMIN# 230000) is a rare lysosomal storage disorder (LSDs) caused by mutations in the FUCA1 gene, leading to alpha-L-fucosidase deficiency; it is inherited as an autosomal recessive trait." (PMID 38053939, 2023). "Fucosidosis is one of the rare autosomal recessive lysosomal storage diseases (LSDs) attributed to FUCA1 variants causing the deficiency of α-L-fucosidase in vivo." (PMID 35820891, 2022). "Mutations of FUCA1 can be found in various cancers and have also been linked to congenital disorders such as fucosidosis." (PMID 36046653, 2022). "Fucosidosis is a rare lysosomal storage disease because of FUCA1 variants that cause the deficiency of α-L-fucosidase in vivo." (PMID 35820891, 2022). "The importance of FUCA1 is exemplified by mutations in the gene, which lead to the congenital lysosomal storage disorder fucosidosis." (PMID 35737835, 2022). "To date, 36 pathogenic variants in the FUCA1 gene have been shown to cause deficiencies of α-L-fucosidase and, thereby, to be linked to fucosidosis." (PMID 33435586, 2021). "All exons and flanking intron regions of FUCA1 were screened by direct sequencing to identify mutations and polymorphisms in three unrelated families with fucosidosis." (PMID 34425818, 2021). "Fucosidosis is a rare autosomal recessive lysosomal storage disease caused by α-l-fucosidase deficiency due to FUCA1 gene mutations." (PMID 34425818, 2021). "The characterization of these mutations aims to elucidate the allelic heterogeneity of fucosidosis phenotypic aspects, thereby providing more information on the impact of the mutant residues on the FUCA1 structure." (PMID 34425818, 2021). "Both genetic analysis of FUCA1 mutations and a positive qualitative urine test based on thin layer chromatography confirmed a diagnosis of fucosidosis, as also in our case." (PMID 33435586, 2021). "Fucosidosis is an autosomal recessive lysosomal storage disease caused by defective alpha-l-fucosidase (FUCA1) activity, leading to the accumulation of fucose-containing glycolipids and glycoproteins in various tissues." (PMID 34425818, 2021). "Here, we report a novel 9-base-pair deletion (NG_013346.1:g.10233_10241delACAGGTAAG) associated with fucosidosis covering the junction between exon 3 (four bases) and intron 3 (five bases) within the FUCA1 sequence." (PMID 33435586, 2021). "In summary, in this study, we identify a novel pathogenic variant in the FUCA1 gene that is linked to fucosidosis." (PMID 33435586, 2021).
fucosidosis (continued). "Fucosidosis (OMIM ≠ 230000) is a rare autosomal recessive lysosomal storage disease caused by a deficiency of the alpha-l-fucosidase enzyme (FUCA1, EC 3.2.1.51; 612280)." (PMID 34425818, 2021). "Fucosidosis (OMIM# 230000) is a lysosomal storage disease (LSD) caused by biallelic pathogenic variants in FUCA1 gene localized on chromosome 1p36.11." (PMID 33266441, 2020). "Fucosidosis is an autosomal recessive disorder induced by biallelic mutations in the structural gene of α-L-fucosidosis (FUCA1)." (PMID 33266441, 2020). "FUCA1 is a lysosomal glycosidase, and mutations in FUCA1 cause the lysosomal storage disorder fucosidosis." (PMID 31521194, 2019). "Fuca1-deficient mice, a promising animal model for human fucosidosis, were shown to display a progressive disease course reminiscent of a milder form of the human condition." (PMID 29706874, 2018). "Fuca1-deficient mice represent a practical and promising model for human fucosidosis, which can be used for pathogenetic and therapeutic studies." (PMID 29706874, 2018). "Recently, Fuca1-deficient mice were generated by gene targeting techniques, constituting a novel animal model for human fucosidosis." (PMID 29706874, 2018). "So far, at least 29 different mutations in the FUCA1 gene on chromosome 1p34 of fucosidosis individuals have been identified, most of them in homozygous form due to high consanguinity." (PMID 27491075, 2016). "Like many other LSDs, fucosidosis lacks a clear genotype-phenotype relationship, and the same homozygous FUCA1 mutation can lead to either the type-1 or the type-2 phenotype." (PMID 27491075, 2016). "Taken together, these results on genomic, transcript and enzyme levels unambiguously confirm Fuca1 deficiency of our mouse model and suggest that it can be used as a reliable fucosidosis animal model." (PMID 27491075, 2016). "Deficiency in human lysosomal α-l-fucosidase (FUCA1) leads to the recessively inherited disorder, fucosidosis." (PMID 29142681, 2015). "Fucosidosis is an ultra-rare and fatal lysosomal storage disease caused by the impaired lysosomal degradation of fucosylated glycoconjugates due to a deficiency in the lysosomal tissue α-L-fucosidase (FUCA1)." (PMID 41200823, 2026). "Biallelic pathogenic variants in the FUCA1 gene are associated with fucosidosis." (PMID 39865383, 2025). "Since FUCA1-deficient fucosidosis patients exhibit, in addition to the accumulation of many fucosylated glycoconjugates, massive storage of Lewis X and H antigen-glycolipids in tissues and urine, it is rather unlikely that FUCA2 has a hydrolytic activity towards these substrates." (PMID 40940767, 2025). "These neuroimaging abnormalities are crucial for diagnosis and contribute to our understanding of the clinical and neuroradiological spectrum of fucosidosis, although definitive diagnosis is confirmed by enzyme activity measurement and identification of pathogenic biallelic FUCA1 variants." (PMID 39865383, 2025). "Thus, both canine and murine disease models indicate that many downstream effects of FUCA1 deficiency contribute to myelin defects in fucosidosis." (PMID 36003149, 2022). "These are the first FUCA1 mutations identified in Tunisia that cause the fucosidosis disease." (PMID 34425818, 2021). "In addition to these mutations, a large number of FUCA1 sequence variations were identified in the Tunisian fucosidosis alleles." (PMID 34425818, 2021). "To date, 36 pathogenic variants in FUCA1 associated with fucosidosis have been documented." (PMID 33435586, 2021). "Only 36 pathogenic variants in the FUCA1 gene are related to fucosidosis." (PMID 33266441, 2020). "Fucosidosis is caused by mutations in the FUCA1 gene resulting in α-L-fucosidase deficiency." (PMID 33266441, 2020). "Thus, Fuca1-deficient mice represent a practical and promising fucosidosis model, which can be utilized for pathogenetic and therapeutic studies." (PMID 29706874, 2018).
fucosidosis (continued). "In order to understand the pathological mechanisms underlying fucosidosis, we generated a constitutive knockout mouse model by inserting the Escherichiacoli neomycin phosphotransferase I (nptI) gene into exon 1 of the Fuca1 gene that encodes lysosomal α-L-fucosidase." (PMID 27491075, 2016). "Further, G418 treatment led to FUCA1 degradation products, impaired enzymatic functionality and cell death, pointing out its disadvantageous use in fucosidosis." (PMID 41200823, 2026). "Individuals with distinct phenotypes can be diagnosed with FUCA1 gene-targeted tests, but fucosidosis has a wide clinical presentation." (PMID 39796208, 2025). "The genetic variability within the FUCA1 gene significantly contributes to the phenotypic variability observed in fucosidosis patients." (PMID 39796208, 2025). "Fucosidosis (OMIM 230,000) is one of the autosomal recessive lysosomal storage diseases (LSDs) caused by variants of FUCA1 (NG_013346) on chromosome 1p36.11." (PMID 35820891, 2022). "Since fucosidosis patients have decreased life expectancy, we examined the viability of Fuca1-null and Fuca1 hemizygous mice over time." (PMID 35737835, 2022). "Here, we report a novel fucosidosis-related 9-base-pair deletion (NG_013346.1:g.10233_10241delACAGGTAAG) affecting the exon 3/intron 3 junction within a FUCA1 sequence." (PMID 33435586, 2021). "To the best of our knowledge, we have described the first molecular analysis of FUCA1 in three unrelated patients with fucosidosis." (PMID 34425818, 2021). "In this study we report a novel fucosidosis-related 9-base-pair deletion (NG_013346.1:g.10233_10241delACAGGTAAG) that covers the exon 3/intron 3 junction within the FUCA1 sequence." (PMID 33435586, 2021). "FUCA1-gene-targeted analysis requires that the clinician determine that fucosidosis is the most probable disease in patient, whereas multigene panel testing proves to be valuable in making differential diagnoses." (PMID 33266441, 2020). "Here, we report the generation of a fucosidosis mouse model, in which the gene for lysosomal α-L-fucosidase (Fuca1) was disrupted by gene targeting." (PMID 27491075, 2016). "To test whether TR can be induced at the fucosidosis stop mutations, we transiently transfected HT1080 cells with plasmids encoding N-terminally Flag-tagged FUCA1 full-length cDNA, wild type (WT) or one of the three selected PTC mutations." (PMID 41200823, 2026). "We next examined whether the weight gain was associated with organomegaly as this is one characteristic of individuals with fucosidosis, and we found that male Fuca1-null mice had increased liver weights when compared with wild-type mice." (PMID 35737835, 2022). "Large increases in mRNA levels of FUCA1 are necessary for the prevention of fucosidosis." (PMID 28245787, 2017). "In addition, a Fuca1 knockout mouse exhibited lysosomal dysregulation, lipid accumulation, neuroinflammation, and behavioral deficits (e.g., impaired coordination and spatial learning) that parallel the motor and intellectual deficits observed in fucosidosis patients." (PMID 36003149, 2022). "Although the genotype-phenotype correlation is still unclear in fucosidosis, it is suggested that patients with the severe and fast-progressing form typically exhibit no FUCA1 activity." (PMID 41200823, 2026). "Both established Fuca1-based fucosidosis mouse models completely lacked any fucosidase activity and exhibited a massive storage of various fucosylated glycoconjugates in numerous tissues and urine, which argues against a functional enzymatic redundancy of both fucosidases." (PMID 40940767, 2025).
breast carcinoma (11 papers, 2015 to 2025). "Mutations of FUCA1 can be found in various cancers, such as breast cancer, lung cancer and central nervous system cancer." (PMID 36046653, 2022). "Lower FUCA-1 expression was associated with recurrences and lower cancer specific survival in breast cancer patients." (PMID 28404918, 2017). "Lower FUCA1 expression was significantly associated with an inferior overall survival rate in breast cancer patients (*P = 0.009)." (PMID 26204487, 2015). "Increased fucosylation in breast cancer cells due to the stable down-regulation of FUCA1 protein expression is associated with malignant transformation, invasion and metastasis." (PMID 26204487, 2015). "In this study, we found that lower FUCA1 expression was associated with highly fucosylated Lewis-x antigens, such as those detected in advanced-stage breast cancer tissues." (PMID 26204487, 2015). "Interestingly, lower FUCA1 expression was associated with highly fucosylated Lewis-x antigens, such as those detected in the advanced-stage breast cancer tissues (indicated by a yellow arrow), and vice versa (H-score data)." (PMID 26204487, 2015). "High FUCA1 expression levels can alter the composition and decrease the quantity of cell surface fucosylation-associated molecules, thereby limiting the invasiveness of early-stage (stage 1 and 2) breast cancer cells." (PMID 26204487, 2015). "While increased FUCA1 expression has been observed in glioblastoma multiforme, papillary thyroid cancer (PTCs) samples, and breast cancer." (PMID 37601653, 2023). "On the other hand, studies have also demonstrated that FUCA1 is required for glioma growth in vitro and in vivo, and transient inhibition of FUCA1 leads to G1-S arrest in breast cancer cells." (PMID 36864055, 2023). "FUCA1 has been identified to effectively reduce the invasiveness of cancer cells in breast cancer through removing fucose-rich polysaccharides on cell surface and inhibiting fucosylation." (PMID 36046653, 2022). "WB and qPCR analysis of FUCA-1 expression in breast cancer-derived cell lines confirmed an inverse relationship with tumor aggressiveness." (PMID 29632639, 2018). "Our results thus showed clearly that negativity to FUCA-1 is significantly related to the development of later recurrences in breast cancer patients with lymph node involvement at diagnosis." (PMID 29632639, 2018). "To confirm the relationship between aggressiveness of breast cancer and expression of FUCA-1, we have analyzed by RT-qPCR FUCA-1-specific mRNA expression in the cohort of LN+ and LN− patients." (PMID 29632639, 2018). "In this study, we investigated the expression of FUCA-1 both at mRNA and protein levels in breast cancer (BC)." (PMID 29632639, 2018). "In this work we studied FUCA-1 expression in breast cancer aggressiveness and prognosis with respect to lymph node involvement." (PMID 29632639, 2018). "FUCA-1 protein and mRNA expression was analyzed in a panel of breast cancer cell lines established from patients with different histotypes of BC tumors." (PMID 29632639, 2018). "We have analyzed FUCA-1 in 305 breast cancer patients by Immunohistochemistry (IHC), and by qPCR in breast cancer patients and in breast cancer cell lines." (PMID 29632639, 2018). "In contrast, other researchers have confirmed that FUCA1 pretreatment significantly reduces the invasive capacity of MDA-MB-231 breast cancer cells." (PMID 30619732, 2018). "We report here that negativity to FUCA-1 is significantly related to the development of later recurrences in breast cancer patients with lymph node involvement at diagnosis." (PMID 29632639, 2018). "On the other hand, higher FUCA-1 expression levels were correlated with a favorable progression free survival (PFS) in a cohort of breast cancer patients." (PMID 28404918, 2017).